LEP (leptin)
Diseases named in the same sentence as LEP in open-access papers (continued):
Sharing a sentence is not in itself a finding about the gene and the disease.
Obesity (continued). "In addition, levels of the pro-inflammatory hormone leptin are increased by obesity and decreases in adiponectin, its anti-inflammatory counterpart, are observed." (PMID 24474939, 2013). "Therefore, further studies regarding the role of leptin in developing abnormal WBC or platelet production in obesity are desirable." (PMID 23617205, 2013). "Future studies regarding whether and how changes in glucose utilization and glucose metabolism are changed by leptin or obese CM may be a mechanistic component of obesity/leptin effect in addition to alterations in mitochondrial respiration." (PMID 24073224, 2013). "However, as common obesity is a state of leptin resistance, the exogenous administration of even exceedingly high doses of leptin has proven relatively ineffective at reducing body weight." (PMID 23092275, 2013). "Since eNOS is the final step for leptin- and adiponectin-induced NO release, alterations in this enzyme might be related with obesity-related endothelial dysfunction." (PMID 24307898, 2013). "Since the cardiac hormones increase lipolysis in obese subjects, as well as helping to alleviate obesity-interrelated hypertension mediated by leptin, this suggests they may be a multi-targeted novel therapy for obesity." (PMID 24137236, 2013). "Leptin is an anti-obesity hormone regulating nutritional intake and energy expenditure." (PMID 23672628, 2013). "Taken together, our findings highlight the different roles that adiponectin and leptin have during obesity development in children and add evidence that perinatal factors may have long lasting effects on metabolic health." (PMID 24205046, 2013). "Although, leptin levels are increased in obesity, obese subjects with type 2 diabetes display reduced leptin levels which may be due to altered fat distribution." (PMID 23853613, 2013). "Our finding of an association between leptin, hsCRP, TNF-α and HOMA with obesity supports the possibility that the increased risk other researchers have observed might be due to a prolonged exposure of arteries to the metabolic milieu." (PMID 24164965, 2013). "While the molecular mechanisms for the obesity-diabetes link remain unclear, the adipocyte hormone leptin seems to be a key factor." (PMID 23936486, 2013). "In brief, an activated leptin gene links to a state of obesity." (PMID 23864899, 2013). "The increased risk in this phenotype may be due to changes in inflammation from altered levels of leptin and adiponectin, increased oxidative stress, and/or obesity induced changes in lung volumes." (PMID 23710195, 2013). "The serum level of leptin is dysregulated in obesity and during the active state of IBD." (PMID 23761791, 2013). "Indeed, leptin levels in humans are correlated with weight gain and therefore increase in obesity, and evidence suggests that resistance to leptin's anorexigenic effects plays a role in this phenomenon." (PMID 24533218, 2013). "However, recent experimental evidence from animal models of obesity suggests that leptin is not only a marker of weight gain but also seems to have a relationship with developing a systemic state of low-grade inflammation and metabolic disturbance." (PMID 23986664, 2013). "NITKO mice of both sexes developed diet-sensitive obesity, increased plasma leptin levels, and increased plasma insulin level, indicating an important role for insulin receptor in the regulation of energy disposal, energy metabolism and perhaps also in reproduction." (PMID 23557393, 2013). "Furthermore, PEG-LPrA2 inhibition of leptin signaling in diet-induced-obesity (DIO) mice treated with a carcinogen, 7,12-dimethylbenz[α]anthracene, (DMBA) delayed the onset of mammary tumors and reduced tumor growth." (PMID 24202338, 2013). "Moreover, in addition to NAMPT, the levels of other adipokines, such as leptin, resistin, and adiponectin, are altered in obesity and periodontal inflammation." (PMID 24288440, 2013).
Obesity (continued). "It has been also suggested that leptin could contribute to serum insulin levels and the development of type 2 diabetes and that leptin is involved in the pathophysiology of obesity and carcinogenesis." (PMID 24146750, 2013). "The suppression of inflammation by quercetin may have clinical significance in preventing cardiovascular disease induced by leptin-resistant in obesity." (PMID 23856194, 2013). "In obesity, serum concentrations of leptin and resistin increase, while adiponectin decreases." (PMID 24288549, 2013). "In addition to insulin, leptin can also be a link between obesity and increased sympathetic activity." (PMID 23573411, 2013). "Even in studies demonstrating a leptin-asthma association, serum leptin does not appear to be the only intermediary factor that explains the obesity-asthma association." (PMID 24288549, 2013). "It has been shown that leptin secretion increases after a meal and this could have hidden the effect of obesity in our measurements." (PMID 23951074, 2013). "Plasma leptin and insulin were both elevated in our experimental model of diet-induced obesity." (PMID 23555678, 2013). "Milk leptin concentration correlates negatively with infant growth in the first two years of life 37–38, suggesting that breastfeeding may confer additional obesity-protective effects for infants of overweight mothers." (PMID 23408760, 2013). "The results might help in the design of new drugs that imitate leptin’s action and contribute to the treatment of obesity and other related disorders." (PMID 24340098, 2013). "In contrast to adiponectin, serum concentration of circulating leptin is elevated in obesity." (PMID 24381591, 2013). "However, in most human with obesity, system leptin levels are often responsively elevated due to the leptin resistance." (PMID 24223863, 2013). "Importantly, exogenous administration of leptin to Lepob/Lepob mice reduces obesity and restores insulin sensitivity." (PMID 23781214, 2013). "Although the relationship among obesity, asthma, and leptin cannot be adequately addressed in this study, we found that BMI is determining factor for leptin; however it did not have a significant association with asthma controls." (PMID 24454412, 2013). "Adiponectin and leptin however could represent an increased systemic inflammatory milieu from obesity." (PMID 23758826, 2013). "In agreement with the increased obesity, KO mice have elevated serum level of leptin." (PMID 24175087, 2013). "Leptin is well known for its anti-obesity and anti-diabetic effects." (PMID 23734095, 2013). "In obesity settings, where hyperleptinemia and hypoadiponectinemia were described, the pro-angiogenic effect of leptin was increased while the anti-angiogenic effect of adiponectin was decreased, thus suggesting the promoting formation of new vessels and the dissemination of tumor cells." (PMID 23554900, 2013). "The more recent findings have corroborated that leptin may signify a link between obesity and metabolic disorders." (PMID 23634778, 2013). "Abnormal LEPR, as well as abnormal leptin catabolism, has been detected in obesity development." (PMID 24051404, 2013). "Leptin’s role in obesity prevents insulin resistance as novel therapeutic interventions of T2DM." (PMID 24131482, 2013). "Serum leptin is proinflammatory, and serum levels are markedly increased in obesity." (PMID 23710195, 2013). "Although AIS is not regarded as an NCD, like them and particularly like obesity, it is often associated with whole organism but opposite metabolic phenomena, namely lower body mass index (BMI), lower circulating leptin levels, and other systemic disorders." (PMID 23448588, 2013). "Therefore, we have investigated the role of leptin in insulin resistance at different levels of obesity controlling for potential confounding factors including lifestyle and diet in a Chinese population." (PMID 23349940, 2013).
Obesity (continued). "Additionally, postnatal overfeeding, or even a genetic susceptibility to diet-induced obesity, can lead to an insensitivity of the ARC to leptin." (PMID 23785312, 2013). "In the present study, we hypothesized that since the levels of cardiac hormones correlate with blood pressure in obesity, the blood pressure-reducing effects of these hormones may be mediated, in part, by decreased leptin production in the hypothalamus." (PMID 24137236, 2013). "Leptin levels are elevated in human obesity and animal models of obesity." (PMID 23762344, 2013). "In case of obesity, increased leptin is considered as an evidence of “leptin resistance”." (PMID 23149391, 2013). "Still, leptin is suggested to exert anti-obesity effects by signaling through “long form” leptin receptors (ObR) abundantly present on both orexigenic neuropeptide Y (NPY)/agouti-related peptide (AgRP) neurons and anorexigenic pro-opiomelanocortin (POMC) neurons in the Arc." (PMID 23554574, 2013). "This suggests that these rats may be more responsive to leptin action, what might confer certain protection against obesity in adulthood." (PMID 24312379, 2013). "However, leptin levels are increased in common obesity in proportion to excess fat mass, raising the possibility of so-called “leptin resistance”." (PMID 23766565, 2013). "Furthermore, following the onset of obesity, both the arcuate and ventromedial hypothalamic nuclei become insensitive to peripheral leptin treatment." (PMID 23649822, 2013). "Collectively, our data indicate that ER treatment could attenuate serum insulin and leptin levels and increase adiponectin in HF-diet induced obese mice which finally may be benefit to obesity and insulin resistance." (PMID 24312343, 2013). "Rose suggested that leptin might be a strong candidate for a role as a proximate effector in mediating the adverse influence of obesity on breast cancer prognosis." (PMID 23826274, 2013). "Leptin biosynthesis is in close direct correlation with insulin level and this may explain the increased leptin levels observed in obesity." (PMID 23061769, 2013). "Finally, we detected a significant protection of leptin antagonist against obese-CM-induced OCR reduction, supporting the important role of leptin in the mitochondrial effect of obesity on colon cancer cells." (PMID 24073224, 2013). "Further, leptin insensitivity may exacerbate HPA dysregulation in obesity and thereby enhance the mass of dysfunctional central adipose stores in a cortisol-dependent manner." (PMID 24109426, 2013). "In order to avoid the influence of adipose tissue and to be sure that variation in leptin levels was not affected by BMI; obese (BMI ≥ 24) subjects were excluded from this study, and therefore the effect of obesity on leptin fluctuation should have been eliminated." (PMID 23853617, 2013). "Metabolic disturbances/dysregulation of markers such as insulin, leptin, glucose, or tryptophan/serotonin could explain the link between obesity, DM2, and depression." (PMID 24229349, 2013). "However, in common obesity, where circulating leptin levels are already high, supplemental leptin therapy has little additional effect on appetite or fat mass." (PMID 23766565, 2013). "In addition to an elevation in circulating levels of growth factors, pro-inflammatory cytokines, and leptin, obesity in postmenopausal women is typically accompanied by higher levels of circulating estrogens." (PMID 23880059, 2013). "More importantly, our result suggest that the increased expression of OBRb in lumbar NP tissues and cells in obesity may participate in leptin transport within the intervertebral disc itself and it has been increased in response to leptin treatment." (PMID 23335226, 2013). "High leptin concentrations may constitute a possible link relating obesity and breast cancer promoting the invasion and migration of tumor cells." (PMID 23061769, 2013).
Obesity (continued). "The VMN contains both leptin and insulin receptors, and isolated deletion of leptin receptors from this nucleus leads to obesity and increased food intake, indicating an important role of the VMN in the function of leptin." (PMID 24400163, 2013). "The inverse association between serum leptin and increased risk of diabetes was independent of obesity in the Atherosclerosis Risk in Communities (ARIC), whereas it was mediated by adiposity and insulin insensitivity in a study among Japanese men and women." (PMID 24455217, 2013). "In summary, the association between leptin and insulin resistance was demonstrated irrespective of obesity levels." (PMID 23349940, 2013). "Leptin, a protein released from adipose tissue, could have significant role in pathogenesis of obesity and type 2 diabetes mellitus." (PMID 23853613, 2013). "Whether the increased MS prevalence in women vs. men is related to the worldwide increased prevalence of obesity and an enhanced immune sensitivity in women to leptin remains to be examined." (PMID 24250904, 2013). "Indeed, it is useful to point out that body weight regulation is also influenced in the case of haploinsufficiency of genes involved in the development of monogenetic obesity such as the leptin gene or the POMC gene." (PMID 24367518, 2013). "Our data revealed that 11 weeks of a high-carbohydrate diet, or the administration of a single intraperitoneal injection of streptozotocin, resulted in a modest model of obesity or diabetes, as demonstrated by changes in body weight, blood glucose levels, plasma insulin, and plasma leptin levels." (PMID 23125848, 2012). "Moreover, the decrease of leptin level in serum of rats treated with EZA can prevent many other disorders related to obesity and hyperlipidemia such as hypertension." (PMID 23258993, 2012). "Based on these data, we propose a model where over-reactivity of the leptin-LepRb signaling system in hypothalamic neurons, including POMC neurons, may play a role in causing leptin resistance and obesity in high-fat fed mice." (PMID 22276206, 2012). "Increased circulating leptin, a marker of leptin resistance, is common in obesity." (PMID 22567283, 2012). "One of these cytokines is leptin, which shows a protective role against obesity." (PMID 23009606, 2012). "A number of studies have proposed that leptin dysfunction provides a link between obesity and AD." (PMID 22254146, 2012). "Severe obesity is depending on a lack of leptin signalling due to mutation of leptin itself (ob/ob) or the leptin receptor (db/db) resulting in an increase of food intake concomitant with a reduction of energy expenditure." (PMID 22701480, 2012). "This warrants some mechanism which may not allow creating the ionic imbalance due to excessive consumption of Zn in diet and preventing the onset of oxidative stress, leptin resistance and protect the consumers from obesity and obesity related diseases." (PMID 22992416, 2012). "Paradoxically, male and female germline Y5 receptor knockout mice are obese with increases in total daily food intake, fasting-induced food intake, body weight and adiposity, and they are not protected against leptin-deficiency-induced obesity." (PMID 22768253, 2012). "Maternal leptin has been shown to program offspring obesity in mammals." (PMID 22958551, 2012). "In addition, the development of resistance to the action of both leptin and insulin, which can occur with age, obesity and inflammation, appears to have a prime role in the pathogenesis of obesity, type 2 diabetes, and other metabolic disorders." (PMID 23115649, 2012). "Since males and females exhibit different lipid metabolism, body fat distribution and percentage, as well as different levels and sensitivity to key metabolic hormones such as leptin or insulin, the choice of sex is also an important issue in studies looking at the effects of anti-obesity drugs." (PMID 22745826, 2012).
Obesity (continued). "Early work showed that acquired defects in the BBB transport of leptin played a role in obesity." (PMID 22612379, 2012). "Indeed, it is known that obesity is triggered by elevated leptin levels and the subsequent development of leptin resistance." (PMID 22254146, 2012). "During obesity it is thought that central hypothalamic resistance to leptin, similar to insulin resistance may take place." (PMID 22537670, 2012). "Indeed, our study certificated that leptin levels declined in overweight and obesity boys in puberty." (PMID 23316228, 2012). "It is possible that the increased level of leptin in obesity might in fact protect the individuals with a higher body mass index after a myocardial infarction." (PMID 23125848, 2012). "So, obesity promoted - hyperinsulinemia stimulates leptin release." (PMID 23067442, 2012). "Similarly, obesity has been identified as a state of leptin resistance in which high circulating levels fail to induce the desired physiologic effect of decreased feeding." (PMID 23152772, 2012). "An alternative explanation is that obesity upregulates the production of both leptin and a cytokine regulating CRP synthesis without a causal relationship between leptin and CRP." (PMID 22533665, 2012). "Impaired leptin transport, especially coupled with central resistance, results in obesity." (PMID 22612379, 2012). "Leptin levels are often elevated in obesity-induced type 2 diabetes, which could be another possible connection to abnormal angiogenesis and cancer." (PMID 22853690, 2012). "Further, leptin may have immuno-regulatory and proinflammatory actions as recognised in obesity and disease states." (PMID 22537670, 2012). "Impaired transport of leptin across the BBB results in obesity and also occurs during starvation." (PMID 22612379, 2012). "In humans, obese individuals possess high values of circulating leptin, which may fail to signal for energy expenditure, suggesting that most human obesity represents a form of leptin resistance." (PMID 22891684, 2012). "Diet-induced obesity elevates the gene expression of leptin." (PMID 22645452, 2012). "Pro- and anti-inflammatory adipokines including leptin and adiponectin are differentially expressed in visceral WAT and are closely associated with plasma adipokine levels during the development of diet-induced obesity." (PMID 22947075, 2012). "Identification of factors regulating adipose MSC cell number and production of proinflammatory adipokine such as MCP-1, as well as dissection of leptin modulated signaling pathway in these cells may help in developing novel anti-obesity target strategies." (PMID 23216800, 2012). "Surprisingly, the finding that the administration of exogenous leptin elevates IGF-1 and TGFβ secretion by rat knee joint cartilage may suggest that increased plasma leptin levels in obesity protect cartilage against degeneration." (PMID 22584415, 2012). "We propose a model where over-reactivity of the leptin-LepRb signaling system in POMC neurons may play a role in development of neuronal leptin-resistance and obesity of high-fat diet fed mice." (PMID 22276206, 2012). "First, rather than the expected increase in leptin/insulin signaling commensurate with increased caloric intake and adiposity, obesity has been associated with reduced sensitivity to leptin/insulin." (PMID 22833718, 2012). "It is fairly well established that leptin could be a major link between obesity and inflammation in CVD." (PMID 22891684, 2012). "However, it has been well documented that under obesity conditions plasma ghrelin levels negatively correlate with BMI and consequently with factors or parameters that are elevated in obesity such as insulin, leptin, and fat mass." (PMID 23162532, 2012). "In obesity, then, the leptin/insulin -> dopamine -> reward chain is inverted at each step." (PMID 22833718, 2012). "In the absence of these mutations and presence of diet-induced obesity, increased adipose tissue results in increased leptin levels." (PMID 22518191, 2012).